NUP58 (nucleoporin 58)
Description:
Component of the nuclear pore complex, a complex required for the trafficking across the nuclear membrane.
Synonyms: KIAA0410; NUPL1; NUP45; PRO2463
Tractability: Antibody: UniProt places it where antibodies can reach, with medium confidence. PROTAC: ubiquitination databases record sites on it; its protein half-life has been measured.
Gene: Protein-coding gene on chromosome 13 (25,301,524 to 25,365,390, forward strand). Ensembl gene ENSG00000139496.
Subcellular location: Nucleus, nuclear pore complex; Nucleus membrane
Pathways (Reactome):
Disease: Defective TPR may confer susceptibility towards thyroid papillary carcinoma (TPC); HCMV Early Events; HCMV Late Events; NEP/NS2 Interacts with the Cellular Export Machinery; NS1 Mediated Effects on Host Pathways; Nuclear import of Rev protein; Rev-mediated nuclear export of HIV RNA; SARS-CoV-2 activates/modulates innate and adaptive immune responses; Transport of Ribonucleoproteins into the Host Nucleus; Viral Messenger RNA Synthesis; Vpr-mediated nuclear import of PICs
Metabolism of RNA: Transport of Mature mRNA Derived from an Intronless Transcript; Transport of Mature mRNA derived from an Intron-Containing Transcript; Transport of the SLBP Dependant Mature mRNA; Transport of the SLBP independent Mature mRNA; snRNP Assembly; tRNA processing in the nucleus
Metabolism of proteins: SUMOylation of DNA damage response and repair proteins; SUMOylation of DNA replication proteins; SUMOylation of RNA binding proteins; SUMOylation of SUMOylation proteins; SUMOylation of chromatin organization proteins; SUMOylation of ubiquitinylation proteins
Metabolism: IP3 and IP4 transport between cytosol and nucleus; IP6 and IP7 transport between cytosol and nucleus; IPs transport between nucleus and cytosol; Regulation of Glucokinase by Glucokinase Regulatory Protein
Cell Cycle: Nuclear Pore Complex (NPC) Disassembly; Postmitotic nuclear pore complex (NPC) reformation
Cellular responses to stimuli: Regulation of HSF1-mediated heat shock response
Immune System: ISG15 antiviral mechanism
Gene Ontology:
Molecular function: protein binding; structural constituent of nuclear pore; identical protein binding; protein-containing complex binding
Biological process: nucleocytoplasmic transport; regulation of protein import into nucleus
Cellular component: nuclear envelope; nuclear membrane; nuclear pore; protein-containing complex
Genetic constraint (gnomAD): Loss-of-function variants: 7 observed, 35.82 expected, observed/expected ratio (o/e) 0.2, 90% interval 0.11 to 0.37. The upper end of that interval is the gene's LOEUF score, 0.37, which puts it in group 1 of 6, group 1 being the genes least tolerant of losing a copy. Missense variants: 487 observed, 529.81 expected, observed/expected ratio (o/e) 0.92, 90% interval 0.85 to 0.99. Synonymous variants: 212 observed, 201.16 expected, observed/expected ratio (o/e) 1.05, 90% interval 0.94 to 1.18.
Homologues: Orthologues: chimpanzee NUP58 (95% identical), dog NUP58 (95% identical), mouse Gm49336 (91% identical), rat Nup58 (89% identical), macaque NUP58 (89% identical), pig NUP58 (88% identical), rabbit NUP58 (88% identical), guinea pig NUP58 (85% identical), tropical clawed frog nup58 (73% identical), zebrafish nup58 (61% identical), Drosophila melanogaster Nup58 (25% identical).
Diseases named in the same sentence as NUP58 in open-access papers:
NUP58 is named in the same sentence as 11 diseases in open-access papers, as found by Europe PMC text mining. Sharing a sentence is not in itself a finding about the gene and the disease. The quoted sentences say what the papers report.
HIV-1 infection (2 papers, 2018 to 2023). The type species of lentivirus and the etiologic agent of acquired immunodeficiency syndrome (AIDS). "By contrast, depletion of Nup62 or Nup214 elevated WT HIV-1 infection, and Nup54 and Nup58 knockdown enhanced infection of both WT and CA mutant HIV-1." (PMID 37355754, 2023). "While the loss of Nup54 and Nup58 elevated infection of WT HIV-1, N74D HIV-1, and P90A HIV-1, removal of Nup62 had a larger positive effect on WT HIV-1 infection." (PMID 37355754, 2023). "Removal of Nup62 subcomplex members (Nup54, Nup58, and Nup62), which are FG-Nups that form a meshwork in the central channel of the pore restricting the flow of cargo larger than 5 nm in diameter, generally elevated both WT and N74D HIV-1 infection." (PMID 37355754, 2023).
chronic myeloid leukemia (1 paper, 2021). "To generate hypomorphic alleles of essential genes, we first sought to confirm the essentiality of candidates NUP58, NUP153, and NUP85 in the human chronic myeloid leukemia near‐haploid cell line HAP1." (PMID 34528284, 2021).
colon cancer (1 paper, 2022). "The transcript levels of four NUPs (NUP210, NUP58, NUP37, and Rae1) were higher in colon cancer tissue among BRD4-bound NUPs." (PMID 35159127, 2022).
type 2 diabetes mellitus (1 paper, 2023). A type of diabetes mellitus that is characterized by insulin resistance or desensitization and increased blood glucose levels. "We also found changes in the expression of nucleoporin genes such as NDC1, NUP35, NUP58, NUP107, NUP160, and POM121C in pancreatic beta cells of patients with type 2 diabetes mellitus." (PMID 37569434, 2023).
infection (3 papers, 2018 to 2024). The state of being infected such as from the introduction of a foreign agent such as serum, vaccine, antigenic substance or organism. "Notably, 9 nucleoporins (NUP58, NUP214, NUP98, NUP54, NUP62, NUP88, NUP153, POM121/NUP121 and RANBP2/NUP358) and the mRNA export factor Rae1 were present in both the CebN infection and transfection interactomes." (PMID 38712050, 2024).
NUP58 also shares sentences with these, for which no sentence is quoted: cancer (2 papers); colorectal cancer (2); cyst (1); infertile (1); lung carcinoma (1); tumor (1).